CD36 (CD36 molecule (CD36 blood group))
Diseases named in the same sentence as CD36 in open-access papers (continued):
Sharing a sentence is not in itself a finding about the gene and the disease.
infection (continued). "It is possible that both Cd36 and Icam1 expression were altered in ceiling LECs by cytokines and chemokines expressed in the dLN in the first 5 days after infection, biasing our gating analysis." (PMID 38194268, 2024). "The function of CD36 is to identify ligands from the pathogen or the host, at which point it triggers the right innate immune response that kills the infection and produces inflammatory cytokines." (PMID 38881887, 2024). "We observed an increase of CD36 positive cells in mice with 5186 strain infection treated with anti-CD25; the high expression of CD-36 can enhance a pro-inflammatory environment favoring alveolar acute damage." (PMID 37284503, 2023). "Here, we provide an important in vivo and in vitro evidence for the role of CD36 in regulation of innate immune response after endotoxin (LPS) infection and TLRs signalling in neonatal brain as well as in immature human microglial cells." (PMID 36759676, 2023). "Our studies demonstrate that SR-B1 and CD36 can be expressed in Sf9 cells using a recombinant baculovirus infection system to induce scavenger receptor expression." (PMID 37625590, 2023). "CD36 can associate with TLR2/6 or TLR4/6 complexes and favor immune response in context of infection or sterile inflammation." (PMID 37996952, 2023). "This suggested that, also in vivo, infection with high-proliferating pathogen correlated with higher CD36 expression." (PMID 37310793, 2023). "Cd36 was expressed in the epithelium and monocytes/macrophages prior to and 6 h after infection, but only monocytes/macrophages at 1d and 2d." (PMID 36092940, 2022). "Increased expression of CD36 was observed in the spleen on D7 before treatment at the peak of infection and inflammation, whereas in the brain, high expression levels were observed in monocyte subpopulations after treatment on D7." (PMID 36310859, 2022). "The authors show that to meet their metabolic needs in response to infection, hematopoietic stem and progenitor cells uptake free fatty acids from their microenvironment via CD36 to fuel fatty acid oxidation." (PMID 35465142, 2022). "On D7, the Ly6Chi and Ly6Clow cell subpopulations were characterized by low expressions of CD36 in the blood and brain compared to the levels observed in the brains of treated mice at this point of infection." (PMID 36310859, 2022). "Quite interestingly, they identify CD36 as the specific FFA transporter responsible for increased FFA uptake during infection." (PMID 35528134, 2022). "Another scavenger receptor, the expression of cluster differentiation antigen 36 (cd36) was upregulated in zebrafish following infection by viral hemorrhagic septicemia virus (VHSV)." (PMID 34025644, 2021). "To confirm the effects of pharmacological inhibition of CD36 in response to infection was consistent with the genetic knockout of CD36 we treated WT (CD36+/+) and CD36 knockout (CD36−/−) animals with LPS for 16 hours." (PMID 34880245, 2021). "Together, these data show that CD36 on HSCs is essential for the uptake of FFA in response to infection." (PMID 34880245, 2021). "Taken together, these studies in the context of the current work suggest that CD36 forms part of a tightly regulated metabolic switch central to the mammalian haematopoietic response to infection." (PMID 34880245, 2021). "Other immune regulatory molecules, such as CD14 and CSF2, were significantly up‐regulated, while others, such as TLR4, IRF9 and CD36, were significantly down‐regulated after infection with H37Rv." (PMID 34632719, 2021). "Knockdown of Cd36 in zebrafish embryos resulted in higher bacterial burden following infection by Mycobacterium marinum." (PMID 34025644, 2021). "The level of CD36 protein and mRNA expression were all significantly inhibited by infection with CD36 mutant (LV3-shRNA) lentivirus in db/db mice." (PMID 34021126, 2021). "Our study finds that during infection HSCs take up FFA as a result of upregulation of the fatty-acid translocase CD36 on the cell surface." (PMID 34880245, 2021).
infection (continued). "By blocking the function of selected integrins using the anti-CD11b and CD36 antibodies, we observe the decreased ability of macrophages of the indirect infection to adhere and cross endothelial cells." (PMID 33946162, 2021). "Here, the authors show in mouse models that infection promotes uptake of long-chain free fatty acids via CD36, which is required for a protective response." (PMID 34880245, 2021). "CD36 was up-regulated by M. tuberculosis H37Ra infection in macrophages and suppressed in exosomes from H37Ra infected macrophages detected by western blotting." (PMID 35069505, 2021). "Collectively, these observations suggest that EPO-induced macrophage CD36 enhances E. coli phagocytosis and promotes infection resolution." (PMID 33927725, 2021). "Similar results were observed for exudate PMN counts and exudate cytokine levels, indicating a role of CD36 in promoting E. coli phagocytosis and infection resolution." (PMID 33927725, 2021). "Using mouse models, we show that inducible CD36 is required for free fatty acid uptake by HSCs during acute infection, allowing the metabolic transition from glycolysis towards β-oxidation." (PMID 34880245, 2021). "Our results demonstrated that SARS-CoV-2 infection increases the CD36 expression in monocytes, suggesting that the increase of lipids uptake can contribute to LD formation, observed after the infection." (PMID 33326472, 2020). "There were several genes whose levels of mRNA expression were significantly (adjusted P< 0.05) different post-infection, including Fcgr1 and Cd36 which were up-regulated and Cd33 which was down-regulated." (PMID 31738750, 2019). "While no defect in LD formation in Cd36-/- BMDM infected with M. tuberculosis and activated with IFN-γ was observed 1 day post-infection, Cd36-/- BMDM had a striking defect in LDs 3 days post infection." (PMID 29370315, 2018). "Arrested CD36+ EPCs gradually switched from early S-phase (BrdU+/DNA2N) at the time of early infection, to late S-phase (BrdU+/DNA4N) and G2-phase (BrdU−/DNA4N) at the time of late infection." (PMID 28264028, 2017). "CD36+ EPCs were incubated with pimozide 6 h prior to infection, and, at 48 h post-infection, numbers of B19V-infected (capsid-expressing) cells were reduced by 4.7-fold and 18.5-fold at 15 μM and 25 μM pimozide, respectively, compared with DMSO-treated cells." (PMID 28459842, 2017). "CD36 was shown to be dispensable for mouse hepatocyte infection by P. yoelii and P. berghei sporozoites." (PMID 28506360, 2017). "Zebrafish (Danio rerio) CD44 and CD154 were significantly up-regulated after stimulating with KLH, while CD36 was down-regulated during infection of Mycobacterium marinum." (PMID 28738780, 2017). "The effect of binding to ICAM-1 or CD36 in pathology and sequestration in vivo during a blood-stage infection with P. chabaudi in mice was investigated." (PMID 28468674, 2017). "In the in vivo experiments, blocking of the Tim-3 pathway resulted in increased CD36 and HO-1 expression in macrophages and decreased L. monocytogenes infection, thus identifying a new mechanism by which Tim-3 induces infection tolerance." (PMID 28205579, 2017). "Infection also elevated the CD36 signal in HDLEC, although the difference between Copenhageni- and Patoc was miniscule, and mainly caused by the increase in punctate morphology." (PMID 28750011, 2017). "CD36-/- and WT BMDMs similarly acidify the PV, which reaches a pH of 4.5 within 15 min post-infection and gradually stabilizes by 1 hour post-infection to an approximate pH of 4.0." (PMID 27280707, 2016). "By one hour post-infection, CD36 was widely distributed on the cell membrane and co-localized with mCherry-Rab7a at numerous cytoplasmic vesicles and at the PV membrane." (PMID 27280707, 2016). "In order to reinforce these findings, WT and CD36-/- BMDMs were stained with the lysotropic dye Lysotracker prior to and 24 h after infection." (PMID 27280707, 2016).
infection (continued). "The number of parasites recovered in WT and CD36-/- macrophage cultures was similar throughout the infection." (PMID 27280707, 2016). "With this approach, 6 scavenger receptors required for resistance to infection were identified, three of which shared homology with mammalian CD36." (PMID 27280707, 2016). "The localization of mCerulean3-tagged CD36 during amastigote infection of human 293T cells was analyzed." (PMID 27280707, 2016). "Concurrently, there was a significant increase in IFNβ gene expression in response to infection and we observed a significant decrease in bacterial phagocytosis (p = 0.031) and CD36 gene expression (p = 0.031) by MDM cultured for 24 h in 50IU/ml IFNβ." (PMID 27701435, 2016). "While infection of 293T cells induced the aggregation of CD36 in the PV within a few hours of infection, mCherry-CD36 expressing iMOs exhibited much more rapid CD36 clustering." (PMID 27280707, 2016). "In the present study, we further deciphered the contribution of SR-A and CD36 scavenger receptors in the control of infection of mice by S. aureus." (PMID 24498223, 2014). "Overall CD36 expression in the lungs from M. tuberculosis- infected guinea pigs increased gradually as the infection progressed." (PMID 22493658, 2012). "Despite the reduced lesion burden seen in BCG vaccinated guinea pigs, there was an increase in CD36 expression by day 60 of infection." (PMID 22493658, 2012). "Increases in CD36 expression were statistically significant on days 30 and 60 of infection (p<0.05 and 0.01 respectively)." (PMID 22493658, 2012). "We next infected both sets of CD36+ EPCs with B19V at a multiplicity of infection (MOI) of 5,000 genome copies (gc)/cell." (PMID 21698228, 2011). "In order to examine the productivity and sustainability of B19V infection of CD36+ EPCs under hypoxia, we passaged B19V preparations harvested from the initial infections under both hypoxia and normoxia, through CD36+ EPCs cultured under each condition." (PMID 21698228, 2011). "After infection with M. tb, intracellular mycobacterial counts progressively increased over 7 days, with fewer M. tb inside Cd36-/- macrophages than Cd36+/+macrophages (p < 0.0001)." (PMID 20950462, 2010). "As the cells harboured both globoside P antigen and CD36, they were considered suitable for a B19 parvovirus in vitro infection assay." (PMID 20209110, 2010). "Reduced TNF in the sera of infected Cd36-/- mice around the peak of infection appears to reflect the reduced mycobacterial stimulus rather than acting as a mediator of antimycobacterial defenses." (PMID 20950462, 2010). "Although the relevance of CD36 in the control of infection has been demonstrated, little is known about the mechanism by which CD36 enhances the response to TLR2 ligands." (PMID 19847289, 2009). "Although these data highlight the role of CD36 in controlling infection with S. aureus and P. falciparum, the mechanism by which CD36 contributes to TLR2 signaling pathway activation has been elusive." (PMID 19847289, 2009). "The present study with bone marrow chimeric mice revealed both beneficial and adverse effects of CD36 in infections with P. berghei ANKA." (PMID 17367535, 2007). "Of further note on the CD36 pathway, it is possible that mice infected with Δpigj strains are more able to phagocytose parasites via CD36, allowing for enhanced infection and escape via the phagosome cellular-invasion route reported for less virulent parasite strains." (PMID 39302131, 2024). "Depending on the route of infection, CD36 may have distinct effects on interactions between mycobacteria and distinct populations of macrophages that mycobacteria first encounter in vivo." (PMID 38881887, 2024). "Interestingly, the scavenger receptor CD36 is closely related to the formation of foam-like macrophages and their lipid metabolism during the infection of M. tuberculosis." (PMID 38881887, 2024).
infection (continued). "During this infection, this pathogen promotes the expression of CD36 and make host cells take up more long-chain fatty acids to produced sufficient ATP through glycolysis or the tricarboxylic acid cycle, allowing it to lurk in host cells for a long time and infect surrounding normal cells." (PMID 38881887, 2024). "Interestingly, we show here that a subset of NK cells expresses a low level of CD36 and that CD36 expression is induced during acute infection with FV." (PMID 38094304, 2023). "Importantly, these CD14+ PMNs expressed APP antigens and exhibited the characteristics of apoptotic cells, as they highly expressed CD24 and CD36, markers of apoptotic PMNs, indicating that these cells play a key role in the recovery stages of infection." (PMID 37705063, 2023). "Interestingly, while infection with proliferation-competent L. major increased CD36 expression as compared with KBMA infection, the effect seemed to be opposite for LDL and long-chain fatty acid uptake." (PMID 37310793, 2023). "Infection with Helicobacter pylori could also increase the expression of CD36 when the stage reaches intestinal metaplasia (IM), both in gastric tissues and in malignant cells." (PMID 37781029, 2023). "(2014) observed an upmodulation of CD36 expression in macrophages followed by an increase of LDs, indicating that CD36 may act in favor of the infection." (PMID 36909724, 2023). "CD36-mediated FFA uptake may offer a therapeutic window for use in emergency condition related to infections." (PMID 35528134, 2022). "CD36 is expressed in corneal and limbal epithelial cells and its primary function appears to be to maintain a physical barrier that prevents bacterial binding and is a key component of resistance to infection." (PMID 36611964, 2022). "DK212 infection substantially repressed CD36, THBS1, and SERPINA1 expression, which might prevent the maturation of immature dendritic cells." (PMID 36059479, 2022). "CD36 acts as a receptor during infection with P. falciparum." (PMID 35964959, 2022). "Consequently, siRNA-mediated depletion of YY1 or PRMT5 rescued ITCH expression, thereby compromising the levels of Mtb-induced ADRP and CD36 and limiting FM formation during infection." (PMID 35658060, 2022). "Only CD36 expression was upregulated in response to LPS or infection in HSPC." (PMID 35528134, 2022). "CD36 is not expressed in HSC at steady state, and CD36-deficiency does not alter HSC repopulation potential in non-infection related context such as classical transplant studies." (PMID 35528134, 2022). "Interestingly, WT microglia dramatically increased Lpl, Fn1 and Cd36 expression after infection, whereas Trem2 ablation resulted in the complete failure to upregulate these genes in microglia." (PMID 36333761, 2022). "CD36 can also bind other ligands, the functions of which during infections is currently unknown and will be important to examine." (PMID 35528134, 2022). "Additionally, H37Ra infection promoted CD36 expression on macrophages but CD36 expression was down-regulated on exosomes from normal macrophages and siRNA-transfected macrophages." (PMID 35069505, 2021). "In order to explore the roles of CD36 in the process of M. tuberculosis infection and the functions of exosomal CD36 in this infection process further, CD36 expression was knocked down using siRNA technology to analyze the interaction between M. tuberculosis and CD36." (PMID 35069505, 2021). "Parasite infection also resulted in appearance of dimeric forms and an additional band in exosome sample between monomeric and dimeric CD36, which may be a complex with other proteins occurred during the release of exosomes." (PMID 34858976, 2021).
infection (continued). "Therefore, our data herein support the involvement of a macrophage PPARγ/CD36 pathway in host infection response." (PMID 33927725, 2021). "We then validated the differentiation ability of CD36−/− HSCs at steady-state and during infection." (PMID 34880245, 2021). "Together these data show that CD36 is an important mediator for the HSC response to infection." (PMID 34880245, 2021). "Nevertheless, low CD36 expression in the serum may promote the infection of M. tuberculosis further in vivo." (PMID 35069505, 2021). "CD36 plays an important role in the transport and uptake of long-chain fatty acids into cells and participates in pathological processes, such as metabolic disorders and infections." (PMID 33326472, 2020). "On classical monocytes, CD36 expression increased further by day 15 post‐infection." (PMID 32566226, 2020). "PFI0005w/PF3D7_0900100 and PFL1955w/PF3D7_1240400 as well as the variant PFL0935c/PF3D7_1219300 turned on at day 25 post infection share the CIDRα3.4 domain predicted to bind CD36 which was not represented in our luminex assay." (PMID 31295334, 2019). "However, our results found that the CD36 expression in splenic macrophages from PbANKA-infected mice was sharply decreased as soon as the first day after infection." (PMID 28824565, 2017). "CD36 participates in the process of apoptosis and Mtb infected macrophages undergoing apoptosis can be phagocytosed by new macrophages induced by intracellular Mtb, thus leading to the expansion of infection." (PMID 28693442, 2017). "To test this hypothesis, we infected CD36+ EPCs with B19V, and at 36 h post-infection (when B19V DNA replication was at its peak), we treated the cells with STAT5-SH2i." (PMID 28459842, 2017). "Therefore, during infection of CD36+ EPCs, B19V employs multiple viral factors and cellular pathways to regulate the cell cycle." (PMID 28264028, 2017). "However, to further evaluate the participation of CD36 in L. major proliferation, the parasite loads of WT and CD36-/- macrophages were monitored during a time course of infection." (PMID 27280707, 2016). "By increasing the sensitivity of macrophages to S-LPS, CD36 might enable detection of fewer bacteria and, consequently, generation of a faster response to infection." (PMID 27073833, 2016). "On the other hand, in later phases of infection, following leakage of serum to the infection site, the CD36-mediated negative regulation may prevent an excessive production of pro-inflammatory cytokines, thereby protecting from septic shock." (PMID 27073833, 2016). "However, the formaldehyde-fixed amastigotes were degraded by macrophages within 6 h of infection and the CD36 aggregates were dispersed." (PMID 27280707, 2016). "We infected BMDMs derived from WT (C57BL/6) or CD36-/- mice with a multiplicity of infection (MOI) of three parasites per macrophage and observed that the size of the PVs was similar between CD36-/- and WT at 8 h post-infection but by 24 h the PVs of WT macrophages were significantly larger." (PMID 27280707, 2016). "In this situation, the delay in CD36 accrual may be caused by expression of LPG and contribute to the delayed PV enlargement often observed in infections started with promastigotes." (PMID 27280707, 2016). "Notably, at 6 h post-infection, when the PV is expanding, CD36 concentrated at the PV membrane juxtaposed to the parasite point of contact." (PMID 27280707, 2016). "Notably, the inhibitor rescued the number of parasites in CD36-/- macrophages at 72 h post-infection, confirming the role of NO in restraining parasite proliferation in the small PVs of CD36-/- macrophages." (PMID 27280707, 2016). "In CD36-/- macrophages, the percentage of LAMP positive PVs was similar to WT at earlier time points (8 h and 24 h), whereas there was significantly lower association of LAMP proteins with PV by 48 h and 72 h post-infection." (PMID 27280707, 2016).